RPL29P19 (ribosomal protein L29 pseudogene 19)
Gene: Transcribed processed pseudogene on chromosome 8 (48,384,590 to 48,385,049, forward strand). Ensembl gene ENSG00000224594.
Diseases named in the same sentence as RPL29P19 in open-access papers:
RPL29P19 is named in the same sentence as 2 diseases in open-access papers, as found by Europe PMC text mining. Sharing a sentence is not in itself a finding about the gene and the disease. The quoted sentences say what the papers report.
head and neck squamous cell carcinoma (1 paper, 2021). A squamous cell carcinoma that arises from any of the following anatomic sites: lip and oral cavity, nasal cavity, paranasal sinuses, pharynx, larynx, and salivary glands. "Another group of five pseudogenes in head and neck squamous cell carcinoma (HNSCC), LILRP1, RP6-191P20.5, RPL29P19, TAS2R2P, and ZBTB45P1, can be used as prognostic or predictive markers." (PMID 34947885, 2021).
RPL29P19 also shares sentences with these, for which no sentence is quoted: tumor (1 paper).